TNF (tumor necrosis factor)
Diseases named in the same sentence as TNF in open-access papers (continued):
Sharing a sentence is not in itself a finding about the gene and the disease.
Neonatal sepsis (49 papers, 2007 to 2025). Systemic inflammatory response to infection in newborn babies. "Three cytokines, IL-6, TNF-α, and IL-1β, were investigated and strongly implicated as diagnostic tools in neonatal sepsis." (PMID 28487810, 2017). "Previous studies demonstrated procalcitonin, TNF-α, and IL-6 to be the most sensitive and specific diagnostic markers of neonatal sepsis." (PMID 28367457, 2017). "The diagnostic value of IL-6, TNF-α, and IL-1β is limited by the time of blood sample collection, which should be as early as possible if neonatal sepsis is suspected, since these cytokines have very short half-life." (PMID 25614712, 2014). "Interleukin-1 has been described as a marker of neonatal sepsis, although its diagnostic efficacy is lower than that of IL-6 and TNF-α." (PMID 25614712, 2014). "We retrieved four studies addressing the association between the SNP TNF-308 and development of neonatal sepsis." (PMID 24310803, 2013). "Neonatal sepsis is a pathological condition associated with elevated levels of pro-inflammatory cytokines, including IL-1β, TNF-α, and IL-6." (PMID 22114550, 2011). "Furthermore, the meta-analysis results suggest a significantly increased risk of neonatal sepsis with the AA+GA, AA genotype of the IL-10-1082 G/A polymorphism in six genetic models and the A allele, AA genotype of TNF-α-308G/A (rs1800629) polymorphism." (PMID 38848433, 2024). "Additionally, the results reveal that the OR value of TNF-α-308G/A (rs1800629) polymorphism merged the allele model was statistically significant (P = 0.016), indicating a significant increase in the risk of neonatal sepsis with the A allele (OR = 1.257, 95% CI: 1.044–1.513)." (PMID 38848433, 2024). "Similarly, a high IL-10/TNF ratio has also been associated with severe late-onset neonatal sepsis." (PMID 25614712, 2014). "Elevated serum levels of several pro-inflammatory cytokines—such as IL-6, IL-8, IL-10, IL-1β, TNF-α, and MCP-1—have been associated with neonatal sepsis." (PMID 40948499, 2025). "First, we assessed the systemic pro-inflammatory response to neonatal sepsis, via quantification of circulating levels of key cytokines (TNF, IFNg, IL- 6, S100 A9, IL- 10, bFGF), chemokines (KC, RANTES, MCP- 1) and growth factors (G-CSF, GM-CSF)." (PMID 40307728, 2025). "During neonatal sepsis in preterm newborns, serum cytokine levels of IL-6 and TNF-α can reach up to 10,000 pg/mL and 1,000 pg/mL respectively." (PMID 38562936, 2024). "These major differences in the production of TNF-α and IL-6 between individuals are also observed in serum samples collected during neonatal sepsis." (PMID 38562936, 2024). "The pro-inflammatory molecules IL-6, IL-8, and TNF-α, which are increased in PHH, have also been associated with neonatal sepsis with PROM." (PMID 38383424, 2024). "IL-6 and IL-12/23p40 are other cytokines that go together with IL-8, IL-10, and TNF-α as biomarkers of prenatal and postnatal inflammation and neonatal sepsis." (PMID 36768650, 2023). "In neonatal sepsis, a positive correlation was observed between sTREM-1 and TNF-α and other pro-inflammatory cytokines such as IL-6 and IL-8." (PMID 35402286, 2022). "As there is ample evidence to show that activated protein C induces a reduction in TNF-α, IL-1β, IL-6, and IL-8 by blocking monocytes/macrophages, protein C has been suggested as potential therapeutic agent in neonatal sepsis." (PMID 35204352, 2022). "In this study, we set out to quantify the eHsp and TNFα in plasma of healthy neonates at term and infants with early-neonatal sepsis." (PMID 34900858, 2021). "In this investigation, we showed that infants with early-onset neonatal sepsis presented increased levels of eHsp-60 and eHsp-70 that are correlated with an increment in TNFα, supporting previous evidence reported by our group and replicating previous reports." (PMID 34900858, 2021).
Neonatal sepsis (continued). "The level of TNFα in healthy neonates at term was 2.94 ± 0.46 pg/ml, with a 3.0-fold increase in infants with early-onset neonatal sepsis (8.96 ± 0.72 pm/ml, p ≤ 0.001)." (PMID 34900858, 2021). "The results indicate that the inflammatory mediators IL-1β, IL-6, IL-8, and TNF-α can be used to diagnose and assess the therapeutic efficacy of neonatal sepsis." (PMID 31671729, 2019). "Nowadays various biochemical markers, such as C-Reactive Protein (CRP), Procalcitonin and tumor necrosis factor alpha, have been proposed as a potential marker for screening neonatal sepsis." (PMID 30069260, 2018). "The neonatal sepsis network was highly associated with immune pathways such as TLR signaling, TNF signaling, leukocyte transendothelial migration, FoxO signaling, and phagosome and platelet activation; this is in accord with the literature." (PMID 28521733, 2017). "For example, TNF-α expression was closely related to neonatal sepsis in very low birth weight infants in Spain." (PMID 29340067, 2017). "Proinflammatory IL-6 and TNF-α are the major cytokines associated with NEC pathogenesis and neonatal sepsis." (PMID 27551722, 2016). "Three trials were included to estimate the use of the TNF-α test in the southern hemisphere at the diagnosis of proven late-onset neonatal sepsis." (PMID 24672322, 2014). "Six articles and eleven trials were included to estimate the use of the TNF-α test in the diagnosis of proven late-onset neonatal sepsis (LONS)." (PMID 24672322, 2014). "At the late-onset neonatal sepsis, the TNF-α test's sensitivity is 0.68, whereas the specificity is 0.89 and the Q* is 0.87." (PMID 24672322, 2014). "In our meta-analysis, the TNF-α tests' sensitivity is 0.66 for the diagnosis of early-onset neonatal sepsis, and the specificity is 0.46 and the Q* is 0.74." (PMID 24672322, 2014). "Eleven articles and twelve trials were included to estimate the use of the TNF-α test in the diagnosis of proven early-onset neonatal sepsis (EONS)." (PMID 24672322, 2014). "Eight trials were included to estimate the use of the TNF-α test in the northern hemisphere at the diagnosis of proven late-onset neonatal sepsis." (PMID 24672322, 2014). "Kocabas (2007) concluded that PCT and tumor necrosis factor-α are best markers in the diagnosis of neonatal sepsis in comparison with IL-6, IL-8 and CRP." (PMID 23493845, 2012). "In contrast tothese reports, in our study, the order of the markers according to sensitivityand specificity for optimum prediction of neonatal sepsis is CRP >PCT > TNF-α > SAA at the time of diagnosis." (PMID 19043563, 2008). "However, in contrast to TNF-α and IL-6, IL-1β serum levels are extremely low (<50 pg/mL) during neonatal sepsis." (PMID 38562936, 2024). "In this context, TNFα has been proposed as a potential immunomodulator in neonatal sepsis." (PMID 35204352, 2022). "Our findings provide new evidence and support previous results showing that infants with early-onset neonatal sepsis with positive blood culture for E. coli, S. epidermidis, and S. dysgalactiae also display marked increase levels of eHsp-60, eHsp-70, and TNFα in plasma." (PMID 34900858, 2021). "Suppressing pro-inflammatory cytokines such as TNF and/or enhancing endogenous IL-10 production might therefore be beneficial in neonatal sepsis." (PMID 33072121, 2020). "Noteworthy, IL-6 and IL-10 have also been recommended as indicators of neonatal sepsis and increased levels of IL-6 and TNFα in vaginal secretions of women with preterm premature rupture of membranes were good predictors of fetal inflammatory response syndrome." (PMID 33396944, 2020). "In the TF-DEG regulatory network, MAPK14 was targeted by CEBPB, indicating that CEBPB targeting MAPK14 might function in neonatal sepsis through TNF signaling pathway." (PMID 30497506, 2018). "The role of TNF-α as a marker for the prediction of early-onset neonatal sepsis has been suggested." (PMID 25614712, 2014).
Neonatal sepsis (continued). "The TNF-α test showed moderate accuracy of the diagnosis of NS both in early-onset neonatal sepsis (sensitivity = 0.66, specificity = 0.76, Q∗ = 0.74) and in late-onset neonatal sepsis (sensitivity = 0.68, specificity = 0.89, Q∗ = 0.87)." (PMID 24672322, 2014). "In this study, TNF-α was considered one of the best markers for the diagnosis of neonatal sepsis, and could be used to assess the effectiveness of the treatment and also the prognosis of the disease." (PMID 24659848, 2014). "Cytokines (IL-6, IL-8 and TNF-α), sCD163, and C-reactive protein were serially measured in an attempt to identify a set of tests which can reliably confirm or refute the diagnosis of neonatal sepsis at an early stage." (PMID 23869218, 2013). "Some cytokines (IL-6, IL-8, and tumor necrosis factor) and cell adhesion molecules (preseason, soluble triggering receptor, and cluster differentiation molecule-64) may have potential applications in treating neonatal sepsis." (PMID 40150583, 2025). "Moreover, both TNF-α and IL-6 levels of septic serum samples were highly increased, and could be used in diagnosis and therapeutic management of neonatal sepsis." (PMID 33382782, 2020). "The remaining doubts about the lack of association between the SNP TNF-308 and development of neonatal sepsis, which had persisted mainly due to the limited sample size of the studies carried out earlier, were subsequently ruled out by a study on 2870 VLBW infants." (PMID 24310803, 2013). "Various laboratory biomarkers such as interleukins (ILs), tumor necrosis factor (TNF), C-reactive protein (CRP), procalcitonin (PCT), and immunoglobulins have been considered for the diagnosis of neonatal sepsis." (PMID 37551395, 2022). "Several biochemical and immunological markers increase in the plasma during neonatal sepsis, such as increased CRP, IL-6, TNF-α, procalcitonin, and E-selectin." (PMID 33233806, 2020). "To evaluate the association of CRP and inflammatory cytokines in the context of neonatal sepsis, we conducted correlation analysis between CRP and the cytokines TNF-α, IL-6, and IL-10." (PMID 28367457, 2017). "In the present study, serum levels of the proinflammatory cytokines TNF-α, IL1-β, and IL-6 and the anti-inflammatory cytokines IL-4 and IL-10 were evaluated for 25 subjects with neonatal sepsis." (PMID 28367457, 2017). "For instance, tumor necrosis factor alpha (TNF-α), interleukin-1-beta (IL-1β), interleukin-6 (IL-6), and CXCL8 (interleukin-8) levels become rapidly and substantially increased during neonatal sepsis." (PMID 28367457, 2017). "The presence of 17 inflammatory proteins including IL-16, TNFα, TNFβ, and MCP-1 were upregulated in neonatal sepsis." (PMID 24772418, 2014). "Among the numerous biomarkers in the field of neonatal sepsis diagnosis, this review identified 8 predominant markers, as determined by number of publications: CRP, PCT, IL-6, IL-8, IFN-γ, TNF-α, CD64 and sICAM." (PMID 23198119, 2011). "First, the cytokines IL-6, TNF, and IL-10 have been found in many studies to be significantly elevated in human infants experiencing LOS, as well as other mouse models of neonatal sepsis." (PMID 40557325, 2025). "GNT treatment decreased LPS-induced elevation of TNF-α, IL-2, and IL-1β expression levels and increased LPS-induced elevation of IL-10 expression levels in the peritoneal fluid, indicating the anti-inflammatory effect of GNT in neonatal sepsis." (PMID 36162982, 2022). "The clinical identification and diagnosis of neonatal sepsis is confirmed by blood culture, and the assessment of acute phase reactants includes C-reactive protein (CRP), procalcitonin, presepsin, and inflammatory mediators such as interleukin-6 (IL-6) and tumor necrosis factor-alpha (TNFα)." (PMID 34900858, 2021). "However, a study shows that there is no variation in the TNF-α, days after installation of neonatal sepsis." (PMID 23401697, 2013).
Neonatal sepsis (continued). "In cases of neonatal sepsis, Fan and Yu (2012) did not recommend the isolated use of inflammatory markers CRP, PCT, interleukin-8 (IL-8), TNF-α and interleukin-1 beta (IL-1β); although IL-6 was rated as superior in relation to the majority of markers, it should not be used in isolation." (PMID 34846061, 2022).
respiratory failure (49 papers, 2010 to 2025). The significant impairment of gas exchange within the lungs resulting in hypoxia, hypercarbia, or both, to the extent that organ tissue perfusion is severely compromised. "Similar results were observed in an Italian study, which confirmed that CT involvement correlates with CRP, IL-6, IL-8, and tumor necrosis factor α (TNF-α) serum levels in severely ill patients with a high risk of acute respiratory failure." (PMID 40428781, 2025). "IL-6 and TNF are linked with fever and with constitutional symptoms, and increase in capillary permeability, hypotension, and acute respiratory failure." (PMID 36982991, 2023). "Third, higher levels of IL-6, IL-8, IL-10, and TNF-α at admission were associated with respiratory failure and disease deterioration." (PMID 34088317, 2021). "Furthermore, IL-6 and TNF-α have been associated with the onset of symptoms, length of hospital stay, respiratory failure and organ damage in many reports." (PMID 39528988, 2024). "ARDS, which was by far the main cause of respiratory failure in the study population, is characterized by persistent elevation in local and systemic levels of cytokines (namely IL-1β, TNF-α, IL-6, and IL-8), which contribute to the progression of lung injury and to extrapulmonary organ dysfunction." (PMID 35995816, 2022). "Interleukins like IL6, IL8 and IL2 along with TNFα might be main causative inflammatory leading respiratory failure." (PMID 32617527, 2020). "We hypothesize that either the surgical procedure mediated by cytokines and tumor necrosis factor or possible toxic effects of oxygen applied during general anesthesia were associated with life-threatening respiratory failure in the patient." (PMID 20814556, 2010). "Ongoing phase II randomized controlled trials (RCTs) of pharmacological therapies targeting calcium release-activated calcium channels and tumor necrosis factor-alpha (TNF-α) aim to prevent further pancreatic necrosis and/or respiratory failure." (PMID 41471355, 2025). "Rapid secretion of large amounts of TNF-α leads to shock, acute respiratory failure/lung damage, hepatocyte apoptosis, adrenal hemorrhage, and DIC." (PMID 39273479, 2024). "Excessive cytokine release, including IL-6, TNF-α, IFNα, INFβ, and INFγ, induces inflammation in the respiratory tract, resulting in airway closure, respiratory failure, and ultimately death." (PMID 39381111, 2024). "PRRSV infection induces the expression and release of a large number of inflammatory factors (such as IL-1β, IL-6, IL-8, TNF-α, etc.), leading to acute inflammation in the lungs, ultimately leading to respiratory failure and death." (PMID 36552462, 2022). "It is reported that the excessive production of inflammatory cytokines, such as TNF-α and IL-1α, induces disseminated intravascular coagulation, respiratory failure, and multiorgan failure." (PMID 35107382, 2022). "Moreover, a positive correlation between the TNF-α/IL-10 ratio and both respiratory failure and disease severity has been documented." (PMID 39061002, 2024). "However, there is controversy if excessive IL-6 synthesis is true a cornerstone of the pathogenesis of respiratory failure in Covid-19 or is just an epiphenomenon of increased IL-1β and TNFα in the cytokine storm." (PMID 33781216, 2021). "Although we could not detect increased specific production of IL-6 in PBMC stimulated with peptide pools due to high background production in controls, we detected a dominant IL-6 and TNF-α response in cell culture supernatants from the patient deceased due to respiratory failure (case 3)." (PMID 32591408, 2020). "Four patients with corticosteroid tapering barriers or ulcers progression post-debridement were treated with combination of TNF-α inhibitors and/or IVIG, and the remission rate was 75% (one patient died of severe respiratory failure)." (PMID 40549753, 2025).
respiratory failure (continued). "Significantly increased SARS-CoV-2-induced IFN-γ, IL-2, and TNF-α production were seen in CD4 + T cells from patients with neurologic involvement and respiratory failure." (PMID 36093351, 2022). "The rapidly progressive nature of respiratory failure corresponds with a cytokine storm, including IL1β, IL6, IL8, TNFα, detected in broncho-alveolar lavage fluids." (PMID 33362557, 2020). "The lectin-like domain of TNF-α can be mimicked by synthetic TIP peptides and represents an innovative pharmacologic option to treat edematous respiratory failure." (PMID 25879802, 2015). "Besides expression of pro-inflammatory cytokines, such as IL-1β and TNF-α, the expression of chemokines CCL2, CCL3, CCL20, CXCL1, CXCL3, CXCL10, IL-8 was shown likely to contribute to clinical observation of excessive inflammatory tissue damage, lung injury, and respiratory failure." (PMID 33362782, 2020).